MTOR (mechanistic target of rapamycin kinase)
Diseases named in the same sentence as MTOR in open-access papers (continued):
Sharing a sentence is not in itself a finding about the gene and the disease.
epilepsy (continued). "mTOR is associated with the pathogenesis of neurological, cognitive, and psychiatric disorders, such as epilepsy, stroke, traumatic brain injury, parkinsonism, spinal cord injury, and Alzheimer’s disease." (PMID 31261959, 2019). "In the brain, excessive activation of mTOR signaling is often linked to the development of epilepsy, and mTOR inhibitors have consistent protective effects in various epilepsy animal models and epileptic patients." (PMID 31632331, 2019). "Brain somatic activating mutations in MTOR have been described in patients with epilepsy caused by focal cortical dysplasia (FCD) type II." (PMID 31780880, 2019). "Recent sequencing efforts in the epilepsy field have linked FCMs to genes regulating the mTOR pathway and, consequently, to local hyperactivation of PI3K/mTOR signaling in the brain." (PMID 31752127, 2019). "Such is the case in mTOR signalling which has been associated with various neuropathlogies such as Autism, Epilepsy, Feeding behavior and age related synaptic alterations." (PMID 31270411, 2019). "Additional experiments in model mice demonstrated the causality from MTOR somatic mutation to epilepsy, as well as the efficacy of rapamycin for the treatment of epilepsy in such cases." (PMID 30087451, 2019). "It was therefore not possible to evaluate the consequences of the approval of this mTOR inhibitor on the treatment patterns of patients with TSC-associated epilepsies." (PMID 31708865, 2019). "This group of syndromes presents with additional neurological manifestations associated with epilepsy and other neuropsychiatric symptoms induced by neuronal mTOR pathway hyperactivation." (PMID 31752127, 2019). "The importance of mTOR signalling for normal brain function was emphasised by the finding that mTOR pathway dysfunction is implicated in disorders such as autism, epilepsy and neurodegenerative disorders." (PMID 31480225, 2019). "Hyperactivation of the mechanistic target of rapamycin (mTOR) pathway has been implicated in CD; however, the mechanisms by which mTOR hyperactivation contribute to the epilepsy phenotype remain elusive." (PMID 29476105, 2018). "In fact, recently animal studies results have suggested mTOR pathway plays a pathogenic role in epilepsy." (PMID 29566708, 2018). "We focused our analysis on the PI3K/Akt, Wnt, insulin, and the mTOR pathways that are linked to both epilepsy and GSK-3 function." (PMID 30237424, 2018). "mTOR plays key roles in brain physiology and pathology as suggested by the numerous neurological disorders associated with mTOR pathway dysfunction, such as epilepsy, autism and neurodegenerative diseases." (PMID 29772672, 2018). "Hyperactive PI3K/Akt/mTOR signaling has been well characterized in epilepsy-associated memory deficits." (PMID 28612047, 2017). "Epileptogenesis is a fertile area of research and everolimus, an inhibitor of the mTor pathway, has demonstrated efficacy in epilepsy associated with TS, showing the clinical potential of this avenue of research for the first time." (PMID 28120042, 2017). "Mutations in MTOR associate with a broad spectrum of phenotypes including epilepsy, hemimegalencephaly, and intellectual disability." (PMID 28554332, 2017). "Remarkably, very recent manuscripts emphasized the role of mTOR upregulation and reduced autophagy as causal mechanisms in epileptogenesis and epilepsy-induce neuronal damage." (PMID 29259984, 2017). "The lowered myelin content correlated with increased mTOR expression and the severe white matter pathology was further linked to the relative duration of epilepsy." (PMID 27750396, 2017). "Accordingly, mTOR signaling disorders are implicated in various diseases, including cancer, epilepsy and ASD10." (PMID 26961412, 2016). "This points to a significant role of mTOR inhibitors in epilepsy, and suggests a potential for the therapy of epilepsy caused by RBP deficiency." (PMID 27855659, 2016).
epilepsy (continued). "AKT and mTOR-related signals have been recently implicated in the pathogenic processes of epilepsy and FCD." (PMID 26961412, 2016). "A number of case reports and retrospective case series as well as two prospective studies evaluating the effect of mTOR inhibitors in overall 162 patients with TSC-associated epilepsies so far showed variable results." (PMID 27809914, 2016). "In the epilepsies, many of the mutations in the mTOR pathway that have been found in patients with brain malformations are somatic mosaic mutations." (PMID 26302787, 2015). "In this study we explored the mTOR pathway activation, through the pattern and cellular distribution of pS6 labelling, in a wide range of pathologies associated with drug-resistant epilepsy." (PMID 25005575, 2014). "It is clear that aberrant mTOR signaling contributes to epilepsy associated with tuberous sclerosis complex." (PMID 24379984, 2013). "Recently, because of its efficacy, cannabidiol, which targets adenosine signaling pathway, has been approved by the U.S. FDA for the treatment of TSC-associated epilepsy, suggesting an anti-epilepsy strategy other than mTOR inhibition is also plausible for TSC." (PMID 41484896, 2026). "The mechanisms of epileptogenesis associated with FCD and hyperactive mTOR signaling remain unclear in DEPDC5-related epilepsy." (PMID 40996830, 2025). "Therefore, given the link between mTOR‐related epilepsy and an increased risk of SUDEP,9, 14 cardiorespiratory monitoring holds significant relevance in clinical settings." (PMID 40971258, 2025). "Interestingly, this contrasts with robust neurological effects observed in preclinical models of epilepsy associated with mTOR pathway hyperactivating variants (“mTORopathies”) where rapamycin prevented seizures and corrected structural abnormalities." (PMID 40620657, 2025). "In one influential study, the authors showed that the epilepsy developed only in animals electroporated with intermediate concentration of plasmid that carried a mutated gene from the mTOR pathway with higher seizure frequency in animals with highest plasmid concentration." (PMID 41366489, 2025). "Mutations of mTOR inhibitors have been identified in severe forms of epilepsy and ASD." (PMID 40704780, 2025). "Epilepsy in Pten-Ric LOF mice likely emerges via mechanisms similar to those in mTOR pathway variants such as TSC that hyperactivate mTORC1 but not mTORC2, although additional effects of mTORC2 inactivation may contribute." (PMID 38446016, 2024). "Inhibition of mTOR and restoration of the excitatory imbalance causing seizures and epilepsy may provide additional benefit for AD and DLB where hyperexcitability may participate in a positive feedback loop." (PMID 38390593, 2024). "mTOR dysfunction results in structural brain abnormalities associated with several psychiatric and neurological disorders, including depression, anxiety, schizophrenia, and epilepsy." (PMID 38365306, 2024). "In addition, alterations of pyridoxal metabolism, mTOR pathway, and redox state that are also associated with epilepsy are also influenced by circadian rhythms." (PMID 36635730, 2023). "Abnormal activation of the mTOR pathway is the pathogenic mechanism of epilepsy in TSC." (PMID 38110931, 2023). "A pathological giant cell without normal tuberin protein is the hallmark of cerebral dysplastic lesions, and abnormal synthesis of synaptic proteins due to hyperactivity of the mTOR pathway may be the cause of epilepsy, ADHD, and ASD." (PMID 37152430, 2023). "Thus, mTOR hyperactivity is linked with disturbances of different molecular signaling which involved in epilepsy." (PMID 37880579, 2023). "PI3K/Akt/Mechanistic target of rapamycin (mTOR) pathway may cause abnormal transduction of neuronal signal in epilepsy under pathological conditions." (PMID 36797447, 2023).
epilepsy (continued). "For example, inadequate myelination of cortical neurons due to disrupted mTOR signaling is a key pathogenic factor in drug-resistant seizures, whereas decreased myelin composition is associated with both the relative length of epilepsy and a higher mTOR expression." (PMID 36675042, 2023). "Specifically, the PIK3CA H1047R variant has been associated with severe somatic or brain overgrowth phenotypes including focal cortical dysplasia with severe epilepsy, whereas the MTOR T1977I variant is associated with megalencephaly and polymicrogyria and overall less severe epilepsy." (PMID 37741456, 2023). "mTOR signaling pathway appears to be associated with the development of autism and epilepsy." (PMID 36819340, 2023). "Furthermore, some types of epilepsy are associated with the up-regulation of the mTOR pathway, and inhibition of this pathway by AMPK activators such as metformin can reduce seizure frequency and severity." (PMID 37880579, 2023). "In any case, mTOR is considered a collaborative molecule for epilepsy pathogenic factors." (PMID 37221133, 2023). "Typically arising from mutations within the mTOR signaling pathway, these disorders are characterized by cortical malformations and other neuromorphological abnormalities that usually co-occur with severe, often treatment-resistant, epilepsy." (PMID 36675042, 2023). "Furthermore, some types of epilepsy are associated with upregulation of the mTOR pathway, and inhibition of this pathway by AMPK activators such as metformin can reduce the frequency and severity of epileptic seizure." (PMID 37737447, 2023). "However, it has been previously suggested that surgical outcome in patients with epilepsy due to mTOR pathway gene mutations is much more successful than in those related to genes involved in channel functions and synaptic transmission." (PMID 37574648, 2023). "Typically arising from mutations within the mTOR signaling pathway, these severe neurological disorders are characterized by overt neuromorphological abnormalities and prominent, often treatment-resistant, epilepsy." (PMID 36675042, 2023). "Similarly, human neural progenitor cells (NPCs) with heterozygous LOF DEPDC5 mutation from epilepsy patients iPSCs displayed elevated mTOR signaling reflected by S6 phosphorylation and larger soma size, which were reversed by rapamycin treatment." (PMID 35359577, 2022). "Notably, the mTOR pathway also plays a critical role in epilepsy and seizures susceptibility in aged rodents, but further investigations are certainly needed to more comprehensively define the role of mTOR signaling in spontaneous seizures in aged mice." (PMID 35572927, 2022). "The mTOR signaling pathway is further implicated in synaptogenesis in normal development and in an epilepsy model, in which increased phospho-S6 levels were associated with dendritic damage that could be reversed by rapamycin." (PMID 35587487, 2022). "mTOR mutations are highly linked with dysplasia, epilepsy, and neurodevelopment disorders." (PMID 36286014, 2022). "A broad range of disease mechanisms underlies the monogenic epilepsies including ion-channel dysfunction, dysregulation of synaptic processes, mechanistic target of rapamycin (mTOR) pathway hyperactivation and impaired chromatin remodelling and transcription regulation." (PMID 34632383, 2021). "Hyperactivation of the mTOR pathway can cause cortical malformations and epilepsy." (PMID 34038402, 2021). "Furthermore, clinical studies have recently shown that mTOR inhibitors are effective not only for tumors, phenotypes predominantly resulting from the second hit, but also for brain dysfunction (epilepsy) caused by a combination of the first and second hits." (PMID 34206526, 2021). "Given that all of these mutations converge on mTORC1 leading to its hyperactivation, pharmacological intervention with mTOR inhibitors (e.g., rapamycin and its analog everolimus) has been proposed as a therapeutic option for epilepsy associated with these MCDs." (PMID 33897381, 2021).
epilepsy (continued). "In addition to promoting epilepsy and its associated pathologies, RhebCA overexpression promotes an increase in neuronal size and cell misplacement strongly suggesting that mTOR hyperactivation directly influences seizure severity." (PMID 34122302, 2021). "The mTOR pathway has been implicated in epilepsy in many human and mouse studies." (PMID 34358226, 2021). "Our findings expand the genotypic and phenotypic spectrum of the NPRL3-associated epilepsy and reveal the mechanisms of mTOR pathway signaling and GATOR1 pathogenesis in focal epilepsies, providing exciting potential for future diagnostic and therapeutic interventions." (PMID 34868250, 2021). "The anatomical and phenotypical features of this novel mouse model, fully recapitulating the most prominent characteristics of MCD (focal lesions and epilepsy), make this a powerful tool and clinically relevant novel model to study the mechanisms underlying mTOR and MCD-related epilepsy." (PMID 34038402, 2021). "Hyperactivation of the mammalian target of rapamycin (mTOR) pathway can cause malformation of cortical development (MCD) with associated epilepsy and intellectual disability (ID) through a yet unknown mechanism." (PMID 34038402, 2021). "Excessive activation of mTOR in microglia impairs CNS homeostasis and causes severe epilepsy." (PMID 33472865, 2021). "Constitutive activation of mTOR signaling represents a shared pathogenic mechanism in a group of developmental malformations that have histopathological and clinical features in common, such as epilepsy, autism, and other comorbidities." (PMID 32140648, 2020). "In particular, a combinatorial therapy targeting different glial cell types and their crosstalk might be translated into disease-modifying treatments for various epilepsies associated with a deregulation of mTOR." (PMID 33041976, 2020). "Furthermore, variants in several genes in the mTOR signaling network cause neurological diseases including epilepsy and autism, and increasing evidence suggests that dysregulation of synaptic transmission is a key feature of these diseases." (PMID 32125271, 2020). "This phenomenon, called mossy fiber sprouting, also appeared in a granule cell–lineage mTOR hyperactivation mouse model, suggesting that epilepsy might be associated with mTOR hyperactivation-induced neuronal restructuring." (PMID 31978189, 2020). "mTORopathies are a heterogeneous group of neurological disorders characterized by malformations of cortical development (MCD), enhanced cellular mechanistic target of rapamycin (mTOR) signaling, and epilepsy that results from mutations in mTOR pathway regulatory genes." (PMID 32457579, 2020). "We hypothesize that this use was due to other TSC-associated conditions and on-going mTOR studies in epilepsy." (PMID 31708865, 2019). "Epilepsy is further tightly linked to mTOR hyper-stimulation and autophagy over-activation." (PMID 31114481, 2019). "Additionally, the direct role of the GC in regulating mTOR activation, a protein kinase consistently associated with epilepsy, gives us new insight for treating so-called “mTORopathies”." (PMID 31134199, 2019). "Thus, loss-of-function PTEN mutations cause upregulation of mTOR and are associated with autism, macrocephaly, and epilepsy." (PMID 30467464, 2018). "Despite extensive research demonstrating a role for the mTOR pathway in CD and other MCDs, the underlying mechanisms by which mTOR hyperactivation lead to epilepsy in these disorders remain unclear." (PMID 29476105, 2018). "In this study we have identified DNA methylation-regulated potential gene networks, pathophysiological pathways including PDGFR, EGFR, NTRK3 (RTKs), and mTOR signalling in addition to several other potential epilepsy-related genes associated with FCD type II pathology." (PMID 30568293, 2018).
epilepsy (continued). "However, the molecular alterations associated with mTOR hyperactivation and candidate mechanisms by which dysregulation of this pathway contribute to epilepsy in these disorders are not well understood." (PMID 29476105, 2018). "Inhibition of mTOR activity can limit aggressive behavior as well as seizure activity, indicating that epilepsy may be closely linked mTOR signaling." (PMID 28966575, 2017). "Hyperactivation of mTOR is associated with several types of epilepsy." (PMID 28966575, 2017). "Additionally, RBPs, mediators of RNA localization and remote expression control, have been linked to epilepsy bridging mTOR signaling with spatially restricted expression." (PMID 27855659, 2016). "Mutations of TSC1 and TSC2 that lead to hyperactive mTOR result in a high incidence of epilepsy." (PMID 23203037, 2012). "The mechanistic target of rapamycin (mTOR) pathway diseases is a group of rare early-onset, hard-to-treat genetic diseases with symptoms ranging from benign tumours in multiple organs to brain malformations causing epilepsy, each of which is managed in disconnected medical disciplines." (PMID 40426219, 2025). "Excessive activation of the mTOR pathway is associated with a cascade of detrimental effects, including structural alterations and neuronal damage, inhibition of autophagy, increased neuroinflammation, and heightened neuronal excitability—all of which are strongly linked to epilepsy." (PMID 40358185, 2025). "Bulk gene expression studies of the brain tissue in the epileptic focus of drug-resistant epilepsy using microarray or RNA-seq showed upregulation of genes associated with neuroinflammation, restructuring of neuronal networks, and activation of the mTOR pathway." (PMID 40026248, 2025). "The excessive activation of mTOR signaling pathway leads to structural changes in neurons, inhibits autophagy, exacerbates neuron damage, affects mossy fiber sprouting, enhances neuronal excitability, increases neuroinflammation, and is closely associated with tau upregulation in epilepsy." (PMID 37221133, 2023). "In addition, mTOR hyper-activation due to Pten deletion has been shown to cause epilepsy." (PMID 37880579, 2023). "Moreover, the underlying molecular mechanism suggests that mTOR inhibitors, such as rapamycin, may be promising drugs for NPRL3-related epilepsy, due to the abnormal activation of the mTOR signaling pathway caused by NPRL3 gene variation." (PMID 36937533, 2023). "Hyperactivation of the mechanistic target of rapamycin (mTOR) signaling pathway is linked to more than a dozen neurologic diseases, causing a range of pathologies, including excess neuronal growth, disrupted neuronal migration, cortical dysplasia, epilepsy and autism." (PMID 36759189, 2023). "Furthermore, cells with mTOR mutations have also shown morphological changes, including enlarged soma and increased dendritic spine density, contributing to hyperfiring and hyperwiring in epilepsy." (PMID 35359577, 2022). "The PTEN/mTOR pathway is a target of miR-21-5p; knockdown of miR-21-5p decreased the number of neuronal deletions and improved the cognitive impairment caused by epilepsy, which suggested that the miR-21-5p/PTEN/mTOR axis might be a potential target for preventing and treating epileptic damage." (PMID 35173580, 2022). "These cells and their interglial crosstalk may offer new insights into the common neurobiological mechanisms underlying epilepsy and the complex cognitive and behavioral comorbidities that are characteristic of the spectrum of mTOR-associated neurodevelopmental disorders." (PMID 33041976, 2020). "On the other hand, it has been recently documented that epilepsy and intellectual disability are clinical manifestations characteristic of phenotypically different disorders associated with cortical developmental malformations secondary to mTOR signaling dysregulation." (PMID 29772672, 2018).